IL36RN (interleukin 36 receptor antagonist)
Diseases named in the same sentence as IL36RN in open-access papers (continued):
Sharing a sentence is not in itself a finding about the gene and the disease.
renal cell carcinoma (1 paper, 2021). "IL36RN encoded an interleukin-36-receptor antagonist in renal cell carcinoma cells, and its overexpression inhibited proliferation, migration, invasion, and colony formation of tumor cells by suppressing β-catenin." (PMID 34332578, 2021).
systemic lupus erythematosus (1 paper, 2025). An autoimmune multi-organ disease typically associated with vasculopathy and autoantibody production. "Additionally, gene set variation analysis (GSVA) identified pathways potentially associated with IL36RN, including the IgA‐producing intestinal immune network, systemic lupus erythematosus, viral myocarditis, apoptosis, T‐cell receptor signaling, and chemokine signaling pathways." (PMID 40347070, 2025).
tumor (14 papers, 2013 to 2025). "The association between IL36RN expression and clinicopathological characteristics was further analyzed, revealing a significant correlation between IL36RN expression in cancer cells and tumor stage (p < 0.05)." (PMID 40347070, 2025). "In summary, IL‐36γ and IL36RN (IL‐36Ra) exhibit an antagonistic interaction within signaling pathways, playing a critical role in regulating inflammatory responses and tumor immunity." (PMID 40347070, 2025). "IL36RN mRNA expression was significantly elevated in GC tissues compared to adjacent non‐tumor tissues." (PMID 40347070, 2025). "Notably, the impact of IL36RN on tumor‐infiltrating lymphocytes and its relevance to GC progression and immunotherapy response remain unexplored." (PMID 40347070, 2025). "Furthermore, therapeutic interventions targeting IL36RN could provide a novel approach to modulate the tumor immune microenvironment, potentially improving clinical outcomes for patients with GC." (PMID 40347070, 2025). "We found that the proteins were significantly modified compared to the control, and immune-related genes such as IL36RN, IL1RN, and NFKBIA were regulated by DAC, which suggested that the immunogenicity of the tumor cell was improved." (PMID 29622799, 2019).
cancer (4 papers, 2019 to 2025). A tumor composed of atypical neoplastic, often pleomorphic cells that invade other tissues. "At the mRNA level, IL36RN has been implicated in tumorigenesis and cancer progression." (PMID 40347070, 2025). "Multivariate Cox regression analysis identified IL36RN expression in both cancer and stromal cells, along with T, N, and TNM staging, as independent prognostic factors (HR > 1, p < 0.05)." (PMID 40347070, 2025). "Additionally, an imaging‐based classification system was employed to delineate cancer nests and stromal regions, allowing for a compartmentalized evaluation of IL36RN expression." (PMID 40347070, 2025).
infection (4 papers, 2021 to 2023). The state of being infected such as from the introduction of a foreign agent such as serum, vaccine, antigenic substance or organism. "At 24 hr post-infection, increases in IL-36RN and IL-36G expressions were detected in both H37Rv- and MKR-infected cells, albeit more increase in IL-36RN and less increase in IL-36G expressions were seen in the MKR-infected macrophages when compared to that of H37Rv-infected cells." (PMID 36242542, 2022).
skin disorder (4 papers, 2020 to 2023). Any deviation from the normal structure or function of the skin or subcutaneous tissue that is manifested by a characteristic set of symptoms and signs. "Loss-of-function homozygous or compound heterozygous mutations in IL36RN, which encodes interleukin-36 receptor antagonist (IL-36Ra), have been implicated in the pathogenesis of skin disorders." (PMID 35927298, 2022). "Loss-of-function homozygous or compound heterozygous mutations in IL36RN, which encodes interleukin-36 receptor antagonist (IL-36Ra), have been implicated in the pathogenesis of various skin disorders." (PMID 32901055, 2020).
immune diseases (1 paper, 2020). "Interleukin-36 receptor antagonist (IL-36Ra) is a new member of the IL-1 family that exhibits anti-inflammatory activity in a variety of inflammatory and immune diseases." (PMID 32742600, 2020).
IL36RN also shares sentences with these, for which no sentence is quoted: inflammatory bowel disease (4 papers); autoimmune disease (3); non-small cell lung carcinoma (3); acrodermatitis continua (2); colitis (2); gastric cancer (2); Obesity (2); pyoderma gangrenosum (2); acne (1); AIDS (1); allergic rhinitis (1); amyotrophic lateral sclerosis (1); atherosclerosis (1); autoimmune thyroid disease (1); autoinflammatory syndrome (1); autosomal recessive congenital ichthyosis (1); bacterial infection (1); benign ovarian tumors (1); cardiac hypertrophy (1); cardiovascular disease (1); chronic recurrent multifocal osteomyelitis (1); chronic rhinosinusitis (1); colon cancer (1); colon tumors (1); colorectal cancer (1); cryopyrin-associated periodic syndrome (1); ectodermal dysplasia (1); Erythema (1); Fever (1); gastric ulcer (1).
A further 16 diseases each share a sentence with IL36RN in 1 paper.